RNU6-102P (RNA, U6 small nuclear 102, pseudogene)
Gene: Small nuclear RNA gene on chromosome 7 (124,647,719 to 124,647,822, forward strand). Ensembl gene ENSG00000207214.
Homologues: Orthologues: chimpanzee U6 (99% identical), macaque U6 (94% identical), rabbit U6 (79% identical), pig U6 (77% identical), dog U6 (74% identical). Paralogues in human: RNU6-1316P (88% identical), RNU6-214P (87% identical), RNU6-639P (87% identical), RNU6-1145P (86% identical), RNU6-283P (86% identical), RNU6-434P (86% identical), RNU6-128P (85% identical), RNU6-140P (85% identical), RNU6-144P (85% identical), RNU6-20P (85% identical), RNU6-211P (85% identical), RNU6-310P (85% identical), and 1290 more.